CD4 (CD4 molecule)
Diseases named in the same sentence as CD4 in open-access papers (continued):
Sharing a sentence is not in itself a finding about the gene and the disease.
viral infection (continued). "During acute viral infections, CD4 T cells differentiate into primarily T helper 1 (Th1) and T follicular helper (Tfh) effector cells." (PMID 25569154, 2015). "In the first model, we assumed that increased availability of target cells due to attraction by inflammatory cytokines facilitates viral infection, which drains the CD4+ T cell population slowly during chronic infection." (PMID 26709961, 2015). "In summary, the stability of the cellular transcriptome profile between weeks 4 and 10 is consistent with maintenance of a resting state of primary CD4+ T cells and limited contribution from viral infection." (PMID 24875931, 2014). "Previous studies have shown that soluble forms of the CD4 receptor (sCD4) can inhibit virus infection and competition between sCD4 and cellular CD4 was proposed as the major mechanism of HIV-1 inhibition by sCD4." (PMID 25423108, 2014). "The efficient activation of at least some CD8 T cells, which gives rise to cytotoxic T lymphocytes (CTL), often critical in containing viral infections and cancer cells, requires help from antigen-specific CD4 T cells." (PMID 24684567, 2014). "In this case, it is more reasonable to assume that the rate of virus infection should be approximately proportionate to the number of healthy CD4+ T cells k1x." (PMID 24829609, 2014). "Detailed properties of CD4+ T-cell immunity during chronic viral infections remain to be defined in contrast to CD8+ T-cell responses." (PMID 25144233, 2014). "Similar numbers of activated CD4+ T cells in the blood are often observed in humans during bacterial 43 and viral infections 44,45, and during super-Ag induced immune responses." (PMID 24114675, 2014). "Statistically higher percentages of CCR4+ CD4 TEM cells (61.94%) distinguished RSV-infected children from other viral infections (52.02%) and healthy controls (42.89%)." (PMID 25013801, 2014). "We also demonstrate that rhSP-D, similar to full length human SP-D, recognizes the envelope glycoprotein gp120 that binds to CD4, initiating an intracellular signaling cascade that sets up viral infection in target cells." (PMID 25036364, 2014). "Both models of CD4+ T cell-lymphopenia manifested protracted viral infection of the liver, indicating that CD4+ T cells are crucial for the initiation of an effective anti-viral immune response during acute viral hepatitis." (PMID 24466045, 2014). "CD4 CTL have also been described during acute viral infections such as influenza, LCMV, and ectromelia virus." (PMID 24586481, 2014). "Cytolytic CD4 T cells (CD4 CTL) have been identified in vivo in response to viral infections; however, the factors necessary for driving the cytolytic phenotype have not been fully elucidated." (PMID 24586481, 2014). "While most studies in mouse models of infection have focused on memory CD8 T-cell generation and maintenance to virus infection, less is understood about memory CD4 T cells and their role in protection and in tissue-specific responses." (PMID 25071787, 2014). "CD4 T cell responses are pivotal in the development of effective cellular and humoral immunity against viral infections." (PMID 25610441, 2014). "bDLE acts by preventing all stages of viral infection by excluding the HIV envelope on infected CD4 cells." (PMID 25196285, 2014). "Our findings indicate that CD4+ T-cell help is required to establish an effective antiviral CD8+ T-cell response in the liver during acute viral infection." (PMID 24466045, 2014). "In fact, during the initial steps of viral infection the virus needs to overcome the mucosal barrier and to find proper target cells such as DCs, macrophages, activated CD4 T cells, to rapidly replicate and spread." (PMID 25250026, 2014). "There were also early indications of memory T-cell heterogeneity in mice based on CD62L expression in antigen-specific memory CD4 T cells generated from virus infection or peptide-specific priming, giving rise to CD62Llo and CD62Lhi memory subsets." (PMID 25071787, 2014).
viral infection (continued). "In contrast to the ability of long-lived CD8+ memory T cells to mediate protection against systemic viral infections, the relationship between CD4+ T cell memory and acquired resistance against infectious pathogens remains poorly defined." (PMID 25473946, 2014). "In contrast, CD4+ T-cell exhaustion remains less well understood, although CD4+ T-cells are critical for the control and elimination of viral diseases." (PMID 25144233, 2014). "We have likewise found that lung CD4 TRM can produce effector cytokines at early time points following secondary viral infection." (PMID 25071787, 2014). "To demonstrate dependence of virus infection on both CD4 and CCR5 levels in this assay system, we used YU-2 and ZM247F viruses to infect 293-Affinofile cells expressing variable levels of both receptors." (PMID 24656066, 2014). "On biological grounds, during primary HIV infection, the rate of virus infection should be approximately proportionate to the virus load k1v because of a small amount of viral load with respect to a large number of CD4+ T cells." (PMID 24829609, 2014). "To investigate in detail alterations in the transcriptome of the CD4+ T cells upon viral infection, we sequenced polyadenylated RNA isolated from Jurkat cells infected or not with HIV-1." (PMID 25462981, 2014). "Clearance of viral infections such as hepatitis B virus and hepatitis C virus is driven by rapid and robust CD4+ and CD8+ T cell responses." (PMID 24971174, 2014). "Following viral infection CD4+ T cell numbers are depleted through increased apoptosis via multiple viral induced pathways." (PMID 25196285, 2014). "Conversely, in the same study it was found that a delay in the appearance of HCMV-specific CD4+ T-cells was accompanied by extended virus replication and viral disease." (PMID 25166270, 2014). "Similar profiles of CD4+ T-cell differentiation in acute-resolving and chronic HBV infection suggested preserved ability of memory CD4+ T-cell generation even during persisting viral infection." (PMID 25144233, 2014). "Although the engagement of CD4 and other chemokine receptors by gp120 is required for viral infection, yet data have shown the involvement of C-type lectins such as DC-SIGN in HIV-1 recognition by binding the HIV-1 gp120." (PMID 23554973, 2013). "In response to viral infection, the number of CD4+ cells and the CD4+/CD8+ ratio both decreased in MCMV-infected control groups (Controls AV, BV, and CV) than in the corresponding virus-free control groups (Controls A, B, and C, resp)." (PMID 23936793, 2013). "Cytotoxic CD8+ cells are the primary cell type that controls these viral infections, but chronic viral infections can also induce the generation of atypical cytotoxic CD4+ cells, which express granzyme B." (PMID 23776639, 2013). "To date, most of the work documenting direct in vivo or ex vivo CTL activity of CD4+T cells has been conducted in systems of experimental or naturally occurring viral infections." (PMID 23565245, 2013). "Accordingly, it appears that the spreading of X4 virus is not only influenced by the ability of mDCs to sensitize CD4+ T cells but also by the capability of mDCs to allow a complete viral life cycle (i.e. productive virus infection)." (PMID 23844079, 2013). "Genetic factors of the patient strongly influence the outcome of viral infection and the response of CD4+T cells." (PMID 23576852, 2013). "More direct evidence for the importance of CD4 T cells responses in the control of chronic viral infections is available from the mouse experimental infection models of LCMV and FV." (PMID 23717308, 2013). "It has been reported that CD4+ T cell-mediated immunity plays a critical role in controlling chronic bacterial and viral infections." (PMID 24010943, 2013). "HIV-1 cell-to-cell transmission is an efficient and rapid way to disseminate viral infection between DC and CD4+cells or between CD4+ T-cells." (PMID 24523981, 2013).
viral infection (continued). "We have demonstrated here that, while IFN-α treatment was unable to efficiently restrict DC-to-T cell HIV-1 transfer, LPS-mediated maturation of DC induced a much more potent blockade of viral infection and transfer in-cis toward autologous CD4+ T cells." (PMID 23311681, 2013). "This quantitative relationship was also detectable when only IFN-associated transcripts were considered, suggesting that both subsets of monocytes show a more complex transcriptional regulation in response to IFN compared to CD4+ T cells in viral infection." (PMID 24391825, 2013). "This study is the first to demonstrate quantitative and qualitative differences between IFN signatures in autoimmunity and viral infection using purified CD4+ T cells and monocyte subsets." (PMID 24391825, 2013). "In contrast, a vaccinia virus infection model revealed that CD4+ T cells specific for an epitope of one protein of the vaccinia virus particle did not enhance the antibody response to another protein of the virion." (PMID 24156704, 2013). "Observations from a number of experimental or natural chronic active viral infections in mice and humans indicate that presence of CD4 T cells and in particular of functional virus-specific CD4 T cells is involved in control of the chronic infection." (PMID 23717308, 2013). "CD4+ T cell response has a key role in driving CD8+ T-cell responses against viral infection in vivo." (PMID 24470869, 2013). "Additional ex vivo virological and immunological studies using myeloid cells and CD4+ T-cells from HIV-1 infected individuals are required to better understand the role of SAMHD1 in viral infection." (PMID 24523981, 2013). "Considerably less is currently known about the regulation and differentiation of CD4 T cell responses during active chronic viral infections." (PMID 23717308, 2013). "The spectrum of tasks which is fulfilled by CD4 T cells in the setting of viral infections is large, ranging from support of CD8 T cells and humoral immunity to exertion of direct antiviral effector functions." (PMID 23717308, 2013). "First, as in other viral infections, CD4 T-cells, specifically memory CD4 T-cells, govern the antiviral immunity against HIV infection." (PMID 24151495, 2013). "While we have seen over the recent years an exciting progress in understanding the regulation of virus-specific CD8 T cells in the setting of persistent and chronic viral infections, much less is known about CD4 T cells." (PMID 23717308, 2013). "On the other hand, increased incidence of human papillomavirus-associated lesions in CD4+ T cell-immunocompromised individuals suggests that CD4+ T cells play a key role in controlling the viral infection." (PMID 23947399, 2013). "Cellular immune responses, consisting of both CD8+ CTL and CD4+ T helper (Th) cells, play an essential role in the control of viral infection." (PMID 23533665, 2013). "Interleukin (IL) -21 is produced by Natural Killer T (NKT) cells and CD4+ T cells and is produced in response to virus infections, where IL-21 has been shown to be essential in adaptive immune responses." (PMID 24358128, 2013). "On the basis of our data and previous reports on chronic viral infection models, we propose that CD4+ CTLs represent another cell sub-type triggered by immune responses upon Brucella infection in addition to CD8+ effector and γδ T cells." (PMID 24367519, 2013). "The role of Th-17 responses during viral infection are poorly characterized, but virus-specific IL-17-producing CD4+ T-cells have been detected in mice following infection with murine-CMV, herpes simplex virus, and influenza virus." (PMID 23071829, 2012). "CD4+ T cells orchestrate immunity against viral infections, but their importance in HIV infection remains controversial." (PMID 22792193, 2012). "A newly identified subset of the CD4+Foxp3+ Tregs, the CD39+ Tregs, has been associated with viral infections and autoimmune diseases." (PMID 22489829, 2012).
viral infection (continued). "Recently, several models of chronic viral infection demonstrated that virus-specific CD4+ or CD8+ T cells producing elevated levels of IL-17 correlated with either viral persistence or a wasting syndrome with a multiple organ neutrophil infiltration." (PMID 22737070, 2012). "IFN-γ, which is produced by PCV2-specific IFN-γ-SCs, is a key immunoregulatory cytokine that controls the differentiation of naïve CD4+ into CD4+ cells and mediates cellular immunity against viral infections." (PMID 23078878, 2012). "Viral infections have been shown to stimulate innate-like B cells to produce CD4 T-cell-independent antibodies by inducing extensive cross-linking of B cell receptors, by engagement with toll-like receptors, or by producing cytokines." (PMID 23133489, 2012). "Our data suggest that low CCR5 expression on CD4 central memory cells protects CD4 cells from direct virus infection and favors the preservation of CD4+ T cell homeostasis." (PMID 23185351, 2012). "To test this possibility, we treated CD4+ T cells with the CB2 agonist JWH-133 with a concentration of drug sufficient to inhibit viral infection (100 nM)." (PMID 22448282, 2012). "It has been shown that Nef can be transferred from HIV-1-infected CD4+ cells to bystander cells upon cell-to-cell contact and contribute to the detrimental effect on bystander cells in viral infection." (PMID 22479639, 2012). "In mammals viral infections can result in biliary atresia and specifically can be related to immune related injury to bile ducts following infiltration of CD4+ T and production of interferon γ." (PMID 22853566, 2012). "We found that activation of CB2R on CD4+ T cells significantly inhibited viral infection in a CB2R -selective and dose-dependent manner." (PMID 22448282, 2012). "Our model considers well-defined parameters for viral infection as well as newly introduced parameters such as the rate at which normal Tregs downregulate CD4+ cells accounts for the rate of change of CD4+ cells in response to normal regulator T-cells." (PMID 22536321, 2012). "This is not surprising since most of the CEF peptides were 8 to 9 mers representing CD8 class I-restricted epitopes, although CD4-specific cytotoxic responses have also been reported in human viral infections." (PMID 22455516, 2012). "In the present study, we found that mice deficient in CD4+ T cells were resistant to EV71 infection as wild-type mice, whereas mice deficient in B cells were highly susceptible to viral infection." (PMID 23133489, 2012). "The data indicate that SIL caused a generalized suppression of T cell expansion, resulting in fewer target cells with CD4 and CXCR4 and/or CCR5 that are susceptible to virus infection." (PMID 22848626, 2012). "In fact, this Vpr effect is at the same level as that seen with Vif, highlighting its important role in viral infection of CD4+ T-cells." (PMID 23134572, 2012). "Th17 cells are CD4+ T cells that produce IL-17 and play a central role in host defence against bacterial, fungal, and viral infections at mucosal surfaces." (PMID 22754568, 2012). "We found that activity of other gp120 antibodies during cell-cell transmission such as 2G12 or V3 loop specific mAbs, which arrest virus infection post-CD4 engagement, can also be substantially reduced during cell-cell transmission." (PMID 22496655, 2012). "Most importantly, there is considerable evidence of an increased frequency of peripheral CD4+CD8+ T cells not only during acute T. cruzi infection but also in viral infections." (PMID 22518275, 2012). "CD4+ T cell-mediated immunity plays a central role in determining the immunopathogenesis of viral infections." (PMID 23251663, 2012). "IL-12 also promotes the polarization of CD4+ T cells to the Th1 phenotype involved against viral infection." (PMID 23185614, 2012). "The infection of B cells, in turn, induces the activation of CD4+ T cells which consequently become more vulnerable to virus infection." (PMID 23029045, 2012).
viral infection (continued). "As our previous research had shown that Th17 cell increased one week after virus infection, we isolated CD4+ T cells by MACS from BALB/c mice one week after CVB3 infection." (PMID 21672246, 2011). "There is, however, considerable evidence of an increased frequency of peripheral CD4+CD8+ T cells during viral infections and during acute T. cruzi infection." (PMID 21858238, 2011). "Some studies have suggested that ES CD4+ T cells that have been activated ex vivo are resistant to viral infection while others have shown that unstimulated CD4+ T cells from these patients are fully susceptible to viral entry and productive infection." (PMID 22141397, 2011). "In other viral infections, the presence of multifunctional CD4/CD8 T cells correlates with viral control." (PMID 22132212, 2011). "The HIV protein, Vpr, is a multifunctional accessory protein critical for efficient viral infection of target CD4+ T cells and macrophages." (PMID 21489275, 2011). "In the context of an acute viral infection, we observed complete redundancy in the roles for IL-6 and IL-21 in Tfh development at the peak of the effector CD4 T cell response." (PMID 21423809, 2011). "The I-A-β-K225R-EGFP animals have normal CD4 T cell populations and are capable of generating antigen-specific antibody in response to model antigens and viral infection." (PMID 21533087, 2011). "Activation of TLR3 signaling prior to viral infection hindered the induction of protective IFN-γ-producing CD4+ and CD8+ T cell populations, but elevated PDL-1 expression and regulatory CD4+ T cell generation in the CNS." (PMID 22189096, 2011). "In contrast, activation of these signals after viral infection improved the induction of IFN-γ-producing CD4+ and CD8+ T cells." (PMID 22189096, 2011). "Further studies will be necessary to evaluate the contribution of CD4+ T cells in immunopathology in these infections, especially in viral infections that are characterized by a late and inefficient induction of neutralizing Abs, such as HIV and HCV." (PMID 21966366, 2011). "In contrast, activation of these signals after viral infection appears to improve the induction of IFN-γ-producing CD4+ as well as CD8+ T cells." (PMID 22189096, 2011). "Classical theories suggest that CD4+ Th1 cells play a vital role against virus infection in adaptive immune responses by production of IFN-γ for effective clearance of virus invasion." (PMID 22151967, 2011). "CD4+ T cells can contribute to protection against viral infection by both indirect and direct manners." (PMID 21347287, 2011). "Although often dispensable for primary T cell responses, CD4 T cell help is known to be a critical component of effective memory CD8 T cell responses to viral infections." (PMID 22046294, 2011). "Activation of TLR3 signaling prior to viral infection hindered the induction of protective IFN-γ-producing CD4+ and CD8+ T cell populations." (PMID 22189096, 2011). "Antibody responses to viral infection are regulated by a network of cells and signaling pathways, including dendritic cells (DCs), CD4 T cells and B cells." (PMID 21998589, 2011). "The impact of virus variation on T-cell function can be profound, and CD4+ escape has been documented in other viral infections, as well as in specific cases in HCV." (PMID 20107020, 2010). "Soon after the identification of CD4+Lin–CD11c–BDCA2/4+CD123+ plasmacytoid dendritic cells as the major IFNα-producing cell type in humans upon virus infection, several groups reported the gradual decline of pDC in peripheral blood of HIV-1 patients." (PMID 20559432, 2010). "Effective priming and maintenance of CD8+ T cell responses to viral infection require ‘help’ from CD4+ T cells, the latter play also a critical role in programming CD8+ T cell memory development." (PMID 20614006, 2010).